ALB (albumin)
Diseases named in the same sentence as ALB in open-access papers (continued):
Sharing a sentence is not in itself a finding about the gene and the disease.
coronary artery disease (continued). "Besides, compared to patients with AoAC ≤ 3, patients with AoAC > 3 have higher CTR, higher AoAC, older age, higher prevalence of coronary artery disease, higher prevalence of cerebrovascular disease, lower albumin, higher total calcium, and higher prevalence of antiplatelet agent use." (PMID 34442433, 2021). "Statistically significant differences between the two groups were observed in the following variables: age, coronary artery disease, NIHSS score, RBC count, FIB level, ALB level, and FAR." (PMID 40376152, 2025). "Tertile comparisons identified significant differences in sex, PEG, CFS score, ischemic heart disease, severe dementia, CRP and albumin (p < 0.05)." (PMID 41356246, 2025). "Statistical significance was found between the two groups for age group, concomitant coronary heart disease, COPD, haemoglobin level below 100 g/L on admission, albumin level below 40 g/L on admission, and increased intraoperative blood loss." (PMID 38355490, 2024). "Recent investigations have revealed that the alkaline phosphatase-to-albumin ratio (APAR) is an essential biomarker of prognosis in several diseases, including cancer, coronary heart disease, and acute renal failure." (PMID 38326383, 2024). "Furthermore, patients with coronary artery disease may have insufficient nutritional intake due to decreased appetite and gastrointestinal dysfunction, which can reduce the synthesis of plasma proteins (including albumin), leading to lower albumin levels." (PMID 39624213, 2024). "The analysis revealed that the primary factors influencing the model’s predictions were AKI stage, albumin (ALB), lactate dehydrogenase (LDH), the use of aspirin, and coronary heart disease (CHD)." (PMID 39211338, 2024). "Those in the LPHB subgroup had elevated BNP but lower prevalence of males and coronary artery disease, and lower LVEF, BMI, and levels of PHE and albumin." (PMID 39064291, 2024). "These predictors included age, CCI, ASA, NRS2002, coronary heart disease, percutaneous coronary intervention, atrial fibrillation, COPD, serum albumin, LVEF, and surgical approach." (PMID 38965472, 2024). "Subsequently, a multivariate logistic regression analysis was conducted, including ALB, CRP, HbA1c, WBC, LEU, urine glucose, coronary heart disease, catheterization, and glucocorticoid usage as variables." (PMID 38771840, 2024). "In recent years, serum fibrinogen-to-albumin ratio (FAR), a novel biomarker for inflammation and thrombosis, has been used to predict the severity and prognosis of coronary artery disease." (PMID 37658287, 2023). "Moreover, because the ratio of serumglobulin to albumin is easy to measure and relatively low in cost, GAR level atadmission may be considered as part of risk stratification when PCI is possiblein patients with coronary heart disease." (PMID 39077558, 2023). "A recent scoring system, the hemoglobin albumin lymphocyte and platelet (HALP) score, combining multi-dimensional metrics, has been used in the prognoses of many diseases except coronary heart disease (CHD)." (PMID 38028472, 2023). "As a newly discovered biomarker composed of neutrophil percentage and albumin level, NPAR has been shown promising in predicting the prognosis of coronary artery disease." (PMID 34346037, 2022). "Ischemia modified albumin (IMA) is closely related to coronary artery disease and can be used as an ideal marker of ischemic heart disease." (PMID 35356504, 2022). "In recent years, the CRP-to-ALB ratio (CAR) has emerged as a novel biomarker for predicting the mortality and prognosis of critically ill patients with coronary artery disease, severe sepsis, or cancer." (PMID 36457873, 2022). "The association between the biomarkers and the outcomes was studied using cause-specific hazard-models, adjusted for age, sex, history of coronary artery disease, NT-proBNP, CKD-EPI-derived eGFR and the urine albumin/creatinine ratio." (PMID 35681209, 2022).
coronary artery disease (continued). "A lower serum albumin level is an independent prognostic predictor of several cardiovascular diseases, such as ACS, coronary artery disease (CAD), and heart failure." (PMID 35211494, 2021). "Univariate Cox proportional hazard analysis demonstrated that independent predictors of all-cause mortality were age, SAS score, progressive AS, history of ischemic heart disease, PAD, serum albumin level, and C-reactive protein level." (PMID 34513029, 2021). "Before surgery, patients who developed emergence delirium were older, received shorter education, and had more coronary heart disease, previous surgery and higher ASA grade; but they had lower hematocrit and albumin levels as well as lower MMSE score." (PMID 32507939, 2020). "Δ phosphate, Δ calcium and Δ albumin were calculated as valueFollow up−valueBaseline Abbreviations: Body mass index (BMI); Vitamin D receptor activators (VDRA); coronary heart disease (CHD); peripheral arterial occlusive disease (PAOD); Interleukin-6 (IL-6)." (PMID 29042624, 2017). "Further forward multivariate analysis revealed a correlation between decreased LVEF and being male, a history of coronary artery disease, advanced CKD stages, low serum albumin level, and ACEI and/or ARB use." (PMID 21860616, 2012). "Age, body mass index (BMI), spot urinary albumin to creatinine ratio (ACR), HbA1c, blood haemoglobin (Hb) at baseline and coronary heart disease during follow-up were predictors of HF-related hospitalization in the training dataset." (PMID 18430204, 2008). "Additionally, a combination of serum albumin and CRP has been studied in patients with coronary artery disease who have undergone PCI, where a findings showed that higher CAR was found to be associated with an increased risk of mortality." (PMID 40636825, 2025). "In recent years, the ratio of ALP to ALB (APAR), as a novel indicator of inflammation and nutritional status, has been shown to be a prognostic biomarker for a variety of diseases, such as cancer and coronary heart disease." (PMID 40371078, 2025). "CAD: Coronary artery disease; CAR: C-reactive protein-to-albumin ratio." (PMID 40922854, 2025). "However, there are few studies on the relationship between perioperative serum albumin (delta albumin or &Alb) and the occurrence of CI-AKI in patients with coronary heart disease after PCI." (PMID 38773489, 2024). "In our cohort, patients who died during hospitalization had a higher heart failure rate because of ischemic heart disease, a higher heart rate, a lower left ventricular ejection fraction, higher CRP levels, lower albumin levels, and worse renal function than those who were discharged alive." (PMID 37234387, 2022). "The patients who died had a significantly higher prevalence of ischemic heart disease; a higher heart rate; higher levels of plasma C-reactive protein, blood urea nitrogen (BUN), and creatinine; a lower serum albumin level; and a lower estimated glomerular filtration rate than surviving patients." (PMID 37234387, 2022). "Nine of them were significantly associated with death, including age, malignancy, CKD with baseline estimated GFR of either 30–89 or <30 mL/min per 1.73 m2, coronary artery disease, HR >120 beats/min, final diagnoses of SJS-TEN overlap and TEN, BUN >10 mmol/L, Hb <10 g/dL, and serum albumin <2 g/dL." (PMID 36091688, 2022). "The significant improvement in serum albumin levels did not change after adjusting for age, coronary artery disease, residual kidney function, and body weight." (PMID 35296793, 2022). "Here, we identified augmented CPP formation and ionised calcium along with reduced total protein and albumin, a major mineralisation inhibitor, in CKD-free patients with established coronary artery disease or cerebrovascular disease in comparison with healthy individuals." (PMID 34830334, 2021).
coronary artery disease (continued). "Although the levels of plasma fibrinogen and albumin have been proven to be in relation to coronary heart disease (CHD), the association between fibrinogen-to-albumin ratio (FAR) and acute coronary syndrome (ACS) has not been adequately investigated." (PMID 34876026, 2021). "Investigations were directed to determine whether serum AGR, fibrinogen, and the fibrinogen-to-albumin ratio (FAR) are related to the presence and severity of coronary artery disease." (PMID 34361562, 2021). "Therefore, a sex-stratified analysis was conducted using Cox models after adjustment for age, coronary heart disease, COPD, APACHE II score, mechanical ventilation, vasopressor use, CRRT, albumin, serum creatinine, and serum urea." (PMID 32587473, 2020). "In model 3, which was a maximally adjusted model containing age, sex, coronary heart disease, COPD, APACHE II score, mechanical ventilation, vasopressor use, CRRT, albumin, serum creatinine, and serum urea, adjusted HR for in-hospital mortality was 2.267 (95% CI: 1.166-4.406, P = 0.016)." (PMID 32587473, 2020). "Older age (OR 1.1, 95% CI 1.05–1.1, P=0.005), ischemic heart disease (OR 2, 95% CI 1.1–3.7, P=0.0197), higher creatinine level (OR 2.3, 95% CI 1.3–4, P=0.0043), and elevated CRP level and CRP-to-albumin ratio (OR 1.1, 95% CI 1.01–1.02, P < 0.0001; OR 1.1, 95% CI 1.02–1.03, P < 0.0001, respectively)." (PMID 31828049, 2019). "Multivariable linear regression demonstrated that older age, non‐ischemic heart disease, increased urea, low hemoglobin and sodium, non‐treatment with ACE‐I/ARB and thiazide, low iron and increased CRP were predictive of low serum albumin (R2 = 0.278, P < 0.0001, Table SS1)." (PMID 30637771, 2019). "Covariates showing initial imbalances included albumin infusion, baseline albumin levels, SOFA score, peak creatinine, peak white blood cell count, peak platelets count, baseline hematocrit, peak potassium, peak urea nitrogen, peak sodium, and coronary artery disease." (PMID 40279952, 2025). "This study aimed to assess circulatory biomarkers related to these mechanisms [albumin, transthyretin, alanine aminotransferase (ALT), aspartate aminotransferase (AST), and C-terminal agrin fragment] and their relationship with muscle mass in people with coronary heart disease." (PMID 36891188, 2023). "Both albumin (ALB) and derived neutrophil to lymphocyte ratio (dNLR) have been shown to be involved in the pathogenesis of coronary artery disease (CAD), chronic inflammatory disease and tumor." (PMID 35369313, 2022). "Patients with coronary artery disease or cerebrovascular disease were characterised by considerably higher CPP yield than healthy blood donors because of increased ionised calcium and reduced albumin, a protein playing a pivotal role in preventing extraskeletal mineralisation by Ca2+ binding." (PMID 34830334, 2021). "Similarly to the results of the current study, meta-analysis of prospective studies showed a positive correlation between coronary heart disease and fibrinogen, C-reactive protein, and leukocyte counts, and a negative correlation with albumin." (PMID 21822486, 2012). "The aim of this study was to investigate the associations of two nontraditional glycemic markers, glycated albumin (GA) and 1,5-anhydroglucitol (1,5-AG), as well as glycated hemoglobin A1c (HbA1c) with coronary artery disease (CAD)." (PMID 25851542, 2015). "The Third Copenhagen City Heart Study showed that microalbuminuria, defined as urinary albumin excretion >4.8 μg/min, was a strong and independent predictor of coronary heart disease and death in hypertensive patients and in participants with no history of coronary heart disease." (PMID 25978637, 2015). "Univariate analysis revealed that at age 80 or over, dyslipidemia, coronary artery disease, chronic heart failure, hemodialysis, nonambulatory status, low ALC, low hemoglobin, and low serum albumin were all significantly correlated with mortality." (PMID 38919317, 2024).
coronary artery disease (continued). "However, data are scarce regarding the role of plasma fibrinogen-to-albumin ratio (PFAR) in patients having SCFP without obstructive coronary artery disease (CAD)." (PMID 37932710, 2023). "The influence of the albumin/derived neutrophil and lymphocyte ratio (ALB-dNLR) on the outcomes of patients with coronary artery disease (CAD) after percutaneous coronary intervention (PCI) is not known." (PMID 35369313, 2022).
acute kidney injury (434 papers, 2005 to 2026). Sudden and sustained deterioration of the kidney function characterized by decreased glomerular filtration rate, increased serum creatinine or oliguria. "In spontaneous bacterial peritonitis (SBP), albumin lowers the risk of acute kidney injury and mortality, particularly in high-risk cirrhotic patients." (PMID 41827398, 2026). "Recent evidence suggests that the fibrinogen-to-albumin ratio is significantly associated with the incidence and severity of acute kidney injury, highlighting its potential clinical utility for risk stratification and prognostication in high-risk populations." (PMID 41525262, 2026). "Low preoperative albumin levels have been associated with a higher rate of infections, bleeding, acute kidney injury, and respiratory failure, as well as prolonged intensive care unit (ICU) and hospital stays." (PMID 40943953, 2025). "Unadjusted and adjusted associations between lactic dehydrogenase to albumin ratio and acute kidney injury." (PMID 41487425, 2025). "When colloid solution is indicated, albumin should be the first choice over artificial colloid solution because of the risk of acute kidney injury and anaphylaxis." (PMID 40551534, 2025). "Study indicates that a blood albumin concentration below 3.8 g/dL (or a decrease in serum albumin levels) is associated with an increased risk of death in individuals suffering from renal failure." (PMID 40069532, 2025). "Both glucose and albumin are associated with chronic inflammation, which plays a vital role in post-contrast acute kidney injury (PC-AKI)." (PMID 38957440, 2024). "Seven key factors, including age, height, albumin, chloride, pneumonia, acute kidney injury (AKI), and heparin use, were associated with respiratory failure risk." (PMID 38007467, 2023). "Other parameters, including serum albumin, serum potassium and blood platelet counts, generally remained within normal range, except when associated with renal failure (serum albumin and potassium)." (PMID 37821590, 2023). "When combined with antibiotics, albumin significantly reduces the risk of renal failure and overall mortality compared with antibiotics alone." (PMID 38139434, 2023). "Chronic heat stress in laying hens increased plasma creatinine and decreased albumin levels, indicating that chronic heat exposure causes renal failure." (PMID 37268977, 2023). "In patients with spontaneous bacterial peritonitis (SBP) and specific risk factors (bilirubin > 4 mg/dL or creatinine > 1 mg/dL), albumin infusion has been shown to decrease the risk of acute kidney injury, and has been associated with improved prognosis." (PMID 37511665, 2023). "The ratio between the platelet count and albumin concentration has been proven to anticipate cardiac surgery-associated acute kidney injury, being associated with a worse prognosis in critical care patients." (PMID 37367406, 2023). "We aimed to evaluate the association between intraoperative 20% albumin administration and acute kidney injury (AKI), along with the duration of hospitalization and 30-day mortality in patients undergoing major abdominal surgery with RBC transfusion." (PMID 36768655, 2023). "In this regard, it has been reported that hospitalized patients with markedly increased serum albumin concentrations have a markedly higher risk for acute kidney injury." (PMID 35805070, 2022). "Age ≥ 65 years, female gender, gastrointestinal tract bleeding, heart failure, acute kidney injury and lower serum albumin were associated with elevated urea-to-creatinine ratio." (PMID 36460694, 2022). "The association between serum ALB redox state and CVDs have been discussed as complications of renal failures." (PMID 33804859, 2021). "Administration of albumin immediately prior to surgery, aiming to increase the albumin level above 40 g/l, was shown to reduce the risk of acute kidney injury after off-pump coronary artery bypass surgery." (PMID 32811539, 2020).